ENG (endoglin)
Diseases named in the same sentence as ENG in open-access papers (continued):
Sharing a sentence is not in itself a finding about the gene and the disease.
endothelial dysfunction (continued). "Endoglin (ENG) is a transmembrane co-receptor of transforming growth factor β (TGF-β) with angiogenic effects, which is involved in various angiogenesis-dependent diseases and associated with endothelial dysfunction, such as PE." (PMID 41210849, 2025). "Alongside immune mechanisms, impaired remodeling of the spiral arteries and syncytiotrophoblast stress lead to the release of anti-angiogenic factors, such as sFlt-1 and soluble endoglin, resulting in endothelial dysfunction, hypertension, and systemic inflammation." (PMID 41373788, 2025). "Markedly higher levels of sEng in the group of deceased patients over the entire seven-day follow-up period might reflect a high degree of endoglin production induced by oxidative stress and, therefore, a high degree of endothelial dysfunction." (PMID 35453325, 2022). "Moreover, desensitization of the PI3K/AKT pathway, which accounted for endothelial dysfunction, was also observed in PE and increased the level of soluble endoglin, an antagonist of TGF-β signaling." (PMID 34295885, 2021). "Thus, in this study, we aimed to evaluate for the first time the effects of long-term LA treatment (up to 15 years) in FH patients on cholesterol levels, biomarkers of inflammation, endothelial dysfunction, and soluble endoglin." (PMID 33640001, 2021). "Designing targeted drugs for endoglin and downstream genes to treat hyperlipidaemia may improve endothelial dysfunction and reduce the incidence of plaque formation and complications." (PMID 34602076, 2021). "In line with the pathogenic hypothesis of an endothelial dysfunction in HHT1, the involvement of ENG in integrin-mediated trans-endothelial leukocyte trafficking was proposed." (PMID 30761306, 2019). "Interestingly, both galectin-3 and endoglin can be expressed as a secreted biomarker in circulation and both have been involved in endothelial dysfunction and inflammation." (PMID 31540324, 2019). "In a study of 288 patients, including 64 with type 2 diabetes, 159 with hypertension, and 65 healthy controls in Spain, plasma soluble endoglin levels were correlated with hyperglycemia and elevated blood pressure, as well as endothelial dysfunction measured by pulse wave velocity." (PMID 29937525, 2018). "We set out to assess whether combining metformin and esomeprazole would additively reduce sFlt-1 and soluble endoglin secretion and reduce endothelial dysfunction (verses drug alone)." (PMID 29466360, 2018). "Despite being related to several cardiovascular pathologies, it is still unclear whether soluble endoglin represents a mere biomarker or it is mechanistically involved in vascular pathology via e.g. induction of endothelial dysfunction." (PMID 25768936, 2015). "In the light of these data, we hypothesized that high levels of soluble endoglin might induce endothelial dysfunction in systemic conduit vessels, such as aorta, in transgenic mice that express high levels of human soluble endoglin (Sol-Eng+)." (PMID 25768936, 2015). "If our hypotheses are confirmed, molecules such as OPG or endoglin could be used as early markers of endothelial dysfunction." (PMID 20459634, 2010). "Thus, Sol-endoglin seems to impair endothelial function, and endothelial dysfunction is a major characteristic of patients with diabetes." (PMID 21171985, 2010). "The EV express sFlt-1 and endoglin that may contribute to endothelial dysfunction." (PMID 34366896, 2021). "Endoglin (also known as CD105) is a membrane co-receptor for transforming growth factor-β, which is released into the circulation in a soluble form and disrupts TGFβ1 signaling in the endothelium, thereby promoting inflammation, endothelial dysfunction, cardiac fibrosis, and vascular remodeling." (PMID 34957261, 2021).
endothelial dysfunction (continued). "Upon the proteolytic processing of the membrane-bound protein, a circulating form of endoglin (soluble endoglin, sEng) can be released, and high levels of sEng have been observed in several endothelial-related pathological conditions, where it appears to contribute to endothelial dysfunction." (PMID 32316263, 2020). "There is a number of reports suggesting that soluble endoglin may be regarded as a biomarker of endothelial dysfunction, for example in pre-eclampsia, atherosclerosis, hypercholesterolemia, diabetes mellitus and hypertension and chronic coronary artery disease." (PMID 25768936, 2015). "Shedding of endoglin and ICAM1 receptors into the systemic circulation during endothelial injury renders them potential circulatory markers of endothelial dysfunction." (PMID 32654473, 2020). "A circulating form of endoglin (alias soluble endoglin, sEng), proteolytically released from the membrane-bound protein, has been observed in several inflammation-related pathological conditions and appears to contribute to endothelial dysfunction and cancer development through unknown mechanisms." (PMID 31540324, 2019). "Endoglin decreases endothelial nitric oxide signaling by inhibiting TGF-β1, leading to endothelial dysfunction." (PMID 22929622, 2012). "The changes in retrotransposon-derived enhancer activities may also play a role in endothelial dysfunction of COVID-19 patients via vascular endothelial growth factor A (VEGFA) and endoglin (ENG) gene dysregulation." (PMID 38003607, 2023). "Furthermore, previous studies have shown that soluble form of placenta-derived endoglin (sENG) was upregulated in the serum of EOPE, which is involved in endothelial dysfunction in coordination with soluble fms-like tyrosine kinase." (PMID 32953262, 2020). "Our results demonstrate that high levels of soluble endoglin alone do not induce endothelial dysfunction in Sol-Eng+ mice." (PMID 25768936, 2015). "In addition, it has been shown that soluble endoglin does not induce endothelial dysfunction under control conditions in vivo." (PMID 29145462, 2017). "However, there are no data showing that high levels of soluble endoglin can induce endothelial dysfunction in aorta of these mice." (PMID 25768936, 2015). "Moreover, LA results in a decrease of biomarkers related to endothelial dysfunction and inflammation (hsCRP, MCP-1, and soluble endoglin) not only after each procedure but also in the long-term evaluation (at least in most patients)." (PMID 33640001, 2021). "At present, circulating soluble endoglin has no predictive value for the progression of CKD, although it could be a biomarker for endothelial dysfunction and new-onset cardiovascular events." (PMID 29937525, 2018).
pulmonary arterial hypertension (43 papers, 2014 to 2025). Pulmonary arterial hypertension (PAH) is a group of diseases characterized by mean pulmonary artery pressure >20 mmHg and elevated pulmonary arterial resistance leading to right heart failure. "Certainly, the association with PoPH is consistent with the reported association of increased plasma soluble endoglin with pulmonary hypertension." (PMID 32454407, 2020). "In 2013, the 5th World Symposium on Pulmonary Hypertension established the ENG gene to be a PAH‐associated gene, since two missense PAH‐associated variants (p.G214S [rs150932144] and p.G545S [rs142896669]) were reported." (PMID 30084161, 2018). "Inhibition of endoglin signalling is associated with pulmonary vascular remodelling in pulmonary hypertension." (PMID 26786759, 2016). "ENG mutations were also found in patients with pulmonary arterial hypertension (PAH), a vascular disorder characterized by the remodeling of small pulmonary vessels, leading to increased right ventricular systolic pressure and ultimately right-sided heart failure." (PMID 37095146, 2023). "Yet, the HHT causative genes ALK1 and ENG together with mutations in BMPRII have been also linked to development of pulmonary arterial hypertension (PAH)." (PMID 37695357, 2023). "The expression of receptors associated with pulmonary hypertension and RV remodeling such as receptor (HTR1B), BMPR2 and endoglin were not affected by MA." (PMID 33789156, 2021). "Other health disorders in which endoglin has been shown to play important roles are preeclampsia (PE) and pulmonary arterial hypertension (PAH)." (PMID 32210029, 2020). "ENG mutations have also been reported in patients with pulmonary arterial hypertension (PAH), a vascular disorder characterized by the remodeling of small pulmonary vessels, resulting in increased right ventricular systolic pressure that ultimately leads to right-sided heart failure." (PMID 31431534, 2019). "Previous studies have shown that TGF-β pathway plays an important role in PAH by regulating pulmonary vascular remodeling, variation of several TGF-β family receptor members, such as ACVRL1, ENG and SMAD9, are pathogenic genes of hereditary pulmonary arterial hypertension patients." (PMID 34310344, 2021). "Seeing that endoglin is determinant in the control of vascular density and that vessel numbers were inversely related to the severity of pulmonary hypertension, here we tried to establish a link between the degree of PH and vascular density in mice after exposure to chronic hypoxia." (PMID 24956016, 2014). "Mutations affecting transforming growth factor-beta (TGF-β) superfamily receptors, activin receptor-like kinase (ALK)-1, and endoglin (ENG) occur in patients with pulmonary arterial hypertension (PAH)." (PMID 24956016, 2014). "Longitudinal follow-up is planned for the proband, with additional genetic testing (e.g., for ENG, MADH4, and GDF2) to be performed if pulmonary hypertension symptoms manifest." (PMID 40933708, 2025). "Moreover, heterozygous mutations in either ENG or ALK1 in humans are associated, in a few cases, with pulmonary arterial hypertension due their functional link with the BMP type II receptor, the main target responsible for most family cases of pulmonary arterial hypertension." (PMID 35665360, 2022). "BMPR: bone morphogenic protein receptor type II; CAV1: caveolin-1; ENG: endoglin; HIV: human immunodeficiency virus; PAH: pulmonary arterial hypertension." (PMID 25165714, 2014). "Lately, various micro-RNAs “miRNAs” and other novel biomarkers like endoglin and asymmetric dimethylarginine “ADMA” might have a role in diagnosis of PH and may differentiate between pulmonary arterial hypertension “PAH” and non-PAH." (PMID 37646902, 2023).
Hypertension (39 papers, 2010 to 2025). The presence of chronic increased pressure in the systemic arterial system. "Increased OS in the placenta has been linked to the release of anti-angiogenic proteins such as endoglin and soluble fms-like tyrosine kinase-1 (sFlt-1), which are known to disrupt normal endothelial function and cause proteinuria and hypertension." (PMID 40565880, 2025). "Thus, we studied the relationship between plasma levels of soluble endoglin and cardiovascular alterations associated with hypertension and diabetes." (PMID 21171985, 2010). "Adjusting for age, sex, race, diabetes, hypertension, smoking, cholesterol, congestive heart failure, peripheral vascular disease, obstructive lung disease, and recruitment site attenuated the association between baseline renal function and circulating endoglin concentration." (PMID 21886815, 2011). "Mothers with hypertension had higher BP, and elevated levels of soluble endoglin at 5 days postpartum." (PMID 34689592, 2021). "Endoglin expression was also correlated with reduced eGFR (p = 0.001), increased creatinine (p < 0.01), increased systolic blood pressure (p < 0.05), hypertension (p < 0.05), and higher IFTA scores (p < 0.001)." (PMID 33081058, 2020). "Increased levels of soluble endoglin have been correlated with hypertension and diabetes, and to have a positive association with increased PWV and retinopathy, suggesting that endoglin plays a vital role in vascular function and development of disease." (PMID 31803759, 2019). "Patients with a higher number (above 25th percentile) of CD34+/KDR+ and CD34+/VE-cadherin+ and lower of CD14+/endoglin+ cells (equal or below 75th percentile) were younger, with less years since diagnosis of hypertension, and with lower BP." (PMID 29304136, 2018). "It is expressed in myofibroblasts, and reduced endoglin levels protect against adverse fibrotic responses in the aortic constriction model of hypertension." (PMID 28494939, 2017). "The sEng+ mice used in the present study have elevated plasma levels of soluble human endoglin and develop mild hypertension and proteinuria as it has been published." (PMID 29145462, 2017). "Shivalingappa reported the placenta-derived soluble TGF-β co-receptor, Endoglin, which is elevated in the sera of preeclamptic individuals, correlated with disease severity as it can induce vascular permeability and hypertension in vivo." (PMID 25392996, 2014). "We observed that plasma Sol-endoglin levels were higher in patients with hypertension and diabetes and in all patients with diabetes with very high cardiovascular risk in the next 10 years compared with patients with mild vascular risk." (PMID 21171985, 2010). "There was also a positive correlation between endoglin levels and Sokolow index in patients with hypertension." (PMID 21171985, 2010). "Our study show that plasma Sol-endoglin levels showed a positive correlation with PWV values in patients with hypertension and diabetes." (PMID 21171985, 2010). "Endoglin levels were also higher in patients with hypertension and diabetes with riser circadian pattern (nocturnal blood pressure increase compared with daytime blood pressure) than in the other patients." (PMID 21171985, 2010). "In our study population, there was a positive correlation between Sol-endoglin plasma levels and basal glycemia in patients with diabetes and hypertension and between endoglin levels and glycated hemoglobin in all patients with diabetes." (PMID 21171985, 2010). "In addition, since ENG has been shown to be up-regulated in various vascular pathologies, including hypertension, stroke and diabetes, it is of great significance to further explore the upstream regulators of elevated ENG expression in AD." (PMID 40702549, 2025). "Increased levels of endoglin may have a role in diabetic retinopathy, hypertension, and the metabolic syndrome, but in our hands it could not differentiate any of the diabetes and CVD groups." (PMID 35996503, 2022).
Hypertension (continued). "In addition, we found that endoglin expression is correlated with several clinical parameters, including eGFR, hypertension, IFTA index score, and serum creatinine level." (PMID 33081058, 2020). "We analysed the predictive value of the ALK1 and endoglin polymorphisms on cardiovascular target organ damage in hypertensive and diabetic patients in 379 subjects with or without hypertension and diabetes in a Primary Care setting." (PMID 32523017, 2020). "Noteworthy, SolEng induces vascular permeability and hypertension in vivo and these effects are compatible with the antagonist role of SolEng on the interaction between membrane bound endothelial endoglin and β1-integrins present in mural cells or in podocytes." (PMID 26646071, 2016). "It has been shown that injection of Sol-endoglin into rats induced hypertension." (PMID 21171985, 2010). "Endoglin is involved in the regulation of endothelial function, but there are no studies concerning its relation with hypertension- and diabetes-associated pathologies." (PMID 21171985, 2010). "However, longer longitudinal studies are required to establish what might be the role of CD14+/endoglin+ cells in the process of atherosclerosis in patients with hypertension." (PMID 29304136, 2018). "Furthermore, endoglin is an angiogenesis/vascular remodeling participator with its soluble form that tends to be increased in inflammatory/vascular pathological conditions (atherosclerosis, hypertension, type 2 diabetes, and dyslipidaemia) and endothelial injury events." (PMID 39767646, 2024). "We observed positive correlations between plasma Sol-endoglin levels and Cornell-VDP in patients with hypertension as well as in all patients with diabetes." (PMID 21171985, 2010). "In the case of patients with diabetes and/or hypertension, we do not know what the origin of the increased plasma Sol-endoglin levels is." (PMID 21171985, 2010). "There was also a strong correlation between pulse pressure and Sol-endoglin plasma levels in patients with diabetes, either with or without hypertension." (PMID 21171985, 2010). "There was a significant correlation between plasma Sol-endoglin concentration and SBP (in both office evaluation and home self-measurement) in patients with diabetes and hypertension and in all patients with hypertension with or without diabetes." (PMID 21171985, 2010).